HCG20 (HLA complex group 20)
Synonyms: AB023051.1; NCRNA00149
Gene: Long non-coding RNA gene on chromosome 6 (30,743,790 to 30,792,250, forward strand). Ensembl gene ENSG00000228022.
Diseases named in the same sentence as HCG20 in open-access papers:
HCG20 is named in the same sentence as 4 diseases in open-access papers, as found by Europe PMC text mining. Sharing a sentence is not in itself a finding about the gene and the disease. The quoted sentences say what the papers report.
migraine (2 papers, 2023 to 2025). "HCG20 is associated with major depressive disorder, that in turn is correlated with migraine." (PMID 37245199, 2023).
brain malformations (1 paper, 2023). "HCG20 is a non-coding RNA gene associated with brain malformations and major depressive disorder." (PMID 37245199, 2023).
pulmonary hypertension (1 paper, 2025). Increased pressure within the pulmonary circulation due to lung or heart disorder. "Targeting regulatory noncoding RNAs can mitigate pathological splicing; in pulmonary hypertension, intervention against the super‐enhancer‐driven lncRNA HCG20 corrects its pathogenic splicing of EIF2AK2 by stabilization U2AF2." (PMID 41399527, 2025). "Similarly, in pulmonary hypertension, the super‐enhancer‐driven lncRNA HCG20 stabilizes U2AF2 and enforces pathogenic splice‐site usage, illustrating how a single dysregulated noncoding RNA can hijack the splicing machinery to drive disease progression." (PMID 41399527, 2025). "In pulmonary hypertension, the super‐enhancer‐driven lncRNA HCG20 binds and stabilizes U2AF2, promoting aberrant splicing of EIF2AK4 and contributing to endothelial dysfunction." (PMID 41399527, 2025).
HCG20 also shares sentences with these, for which no sentence is quoted: major depressive disorder (1 paper).